USP9X (ubiquitin specific peptidase 9 X-linked)
Diseases named in the same sentence as USP9X in open-access papers (continued):
Sharing a sentence is not in itself a finding about the gene and the disease.
esophageal squamous cell carcinoma (4 papers, 2013 to 2024). Esophageal squamous cell carcinoma (ESCC) is a type of esophageal carcinoma (EC) that can affect any part of the esophagus, but is usually located in the upper or middle third. "CypA/MMP9 signal pathway and up-regulation of USP9X may be attributed to the malignant transformation of esophageal squamous cell carcinoma (ESCC)." (PMID 25047112, 2014).
gastric cancer (4 papers, 2021 to 2024). A primary or metastatic malignant neoplasm involving the stomach. "This study aims to investigate the interaction between MTH1 and a deubiquitinase, USP9X, in regulating the proliferation, survival, migration, and invasion of gastric cancer cells." (PMID 39075342, 2024). "USP9X stabilizes MTH1 to promotes gastric cancer cell growth, survival, migration, and invasion." (PMID 39605891, 2024). "siRNAs were used to interfere with USP9X expression in gastric cancer cell lines HGC-27 and MKN-45." (PMID 39075342, 2024). "Hsa_circ_0008434/miR-6838-5p/USP9X promotes gastric cancer progression." (PMID 39605891, 2024). "The interaction between USP9X and MTH1 was evaluated by co-immunoprecipitation (co-IP) in HGC-27 gastric cancer cells." (PMID 39075342, 2024). "USP9X interacts with and stabilizes MTH1 to promote the proliferation, survival, migration and invasion of gastric cancer cells." (PMID 39075342, 2024). "Previous studies demonstrated that USP7, USP9X and USP22 stabilize PD-L1 in gastric cancer, oral squamous cell carcinoma or liver cancer, respectively." (PMID 38167274, 2024).
medulloblastoma (4 papers, 2013 to 2026). A malignant, invasive embryonal neoplasm arising from the cerebellum. "SOX2 co-immunoprecipitation identified a number of interacting proteins in medulloblastomas cells, including Usp9x and Usp34." (PMID 33613844, 2021). "In addition, SOX2 interacts with deubiquitinases Usp34 and Usp9x which can lead to SOX2 stabilization in medulloblastoma cells and was also shown in embryonic stem cells." (PMID 33613844, 2021). "Together, our studies identify a large set of SOX2-associated proteins in DAOY medulloblastoma cells and identify two proteins, MSI2 and USP9X, that warrant further investigation to determine whether they are potential therapeutic targets for brain cancer." (PMID 23667531, 2013).
osteosarcoma (4 papers, 2021 to 2024). A usually aggressive malignant bone-forming mesenchymal neoplasm, predominantly affecting adolescents and young adults. "USP9X was significantly upregulated in human osteosarcoma cell line SaOS2 expressing prostate-specific antigen." (PMID 34112167, 2021). "In addition, USP9X is also involved in the proliferation, migration, and invasion of osteosarcoma by regulating the ERK1/2 and PI3K/Akt signaling pathways." (PMID 39062505, 2024). "It was shown that SOX2 levels are regulated by Usp9x in osteosarcomas." (PMID 33613844, 2021). "Molecules such as UBE2T, E3 ubiquitin ligase adaptor SPOP, USP9X, USP22, and BAP1 are involved in regulating the proliferation, migration, and invasion of osteosarcoma cells through modulation of the PI3K/Akt signaling pathway." (PMID 39062505, 2024). "A recent study found that the deubiquitinase USP9X stabilizes the oncogene SOX2 protein expression through its deubiquitinating activity, and SOX2 mediates the promoting effect of USP9X on osteosarcoma cell proliferation." (PMID 39062505, 2024).
ovarian carcinoma (4 papers, 2018 to 2025). A malignant neoplasm originating from the surface ovarian epithelium. "More convincingly, endogenous HIF-2α was present in the USP9X immunoprecipitates from multi species-derived ovarian cancer cells." (PMID 40246814, 2025). "Encouragingly, USP9X inhibitor conferred the ovarian cancer cells higher sensitivity to chemotherapeutic agents, and reduced the IC50 significantly (CDDP: IC50: 5.882 μM vs. 1.278 μM for CAOV3; 5.568 μM vs. 2.107 μM for ID8; PTX: IC50: 5.058 nM vs. 3.026 nM for CAOV3, 5.887 nM vs. 2.663 nM for ID8)." (PMID 40246814, 2025). "Genetic ablation of USP9X markedly reduced GS protein levels in U251 and U343 GBM cell lines as well as in SKOV3, an ovarian cancer cell line." (PMID 40162736, 2025). "We then transiently overexpressed Smad2 and Smad3 in ovarian cancer cells, CAOV3 and SKOV3, respectively, and found that only the overexpression of Smad2 increased the mRNA levels of USP9X." (PMID 40246814, 2025). "Whether USP9X participates in TGF-β signaling controlled pathological events and therapeutic response in ovarian cancer progression is thus worthy exploring." (PMID 40246814, 2025). "In contrast, we did not observe copy number changes of USP9X in the majority of malignancies including lung and ovarian cancer." (PMID 29335437, 2018). "In this study, we find that in certain lung and ovarian cancer cell lines, USP9X knockdown does not alter MCL1 protein levels." (PMID 29335437, 2018). "Therefore, specific functional domains within USP9X and HIF-2α mediate the direct molecular binding, which could be involved in ovarian cancer regulation." (PMID 40246814, 2025). "Indeed, we found that USP9X knockdown did not convincingly alter MCL1 protein levels in multiple lung and ovarian cancer cell lines." (PMID 29335437, 2018).
Parkinson disease (4 papers, 2013 to 2025). A progressive degenerative disorder of the central nervous system characterized by loss of dopamine producing neurons in the substantia nigra and the presence of Lewy bodies in the substantia nigra and locus coeruleus. "USP9X is also known to deubiquitinate α-synuclein, which is central to the pathogenesis of Parkinson disease (PD)." (PMID 31130875, 2019). "Usp9x also deubiquitylates mono-ubiquitylated alpha-synuclein raising the possibility it may play a role in the progression of neurodegenerative diseases such as Parkinson’s disease." (PMID 23861879, 2013). "Notably, the knockdown of USP9x induces the formation of toxic α-synuclein inclusions USP9X in SH-SY5Y cells upon proteolytic inhibition 405, indicating its role for neuroprotection, but its dysfunction may trigger Parkinson’s disease." (PMID 40703332, 2025).
renal carcinoma (4 papers, 2016 to 2025). A carcinoma arising from the epithelium of the renal parenchyma or the renal pelvis. "Taken together, these results provide the first evidence that IITZ-01 enhances TRAIL-mediated apoptosis through DR5 stabilization by downregulation of Cbl and USP9X-dependent survivin ubiquitination and degradation in renal carcinoma cells." (PMID 32825566, 2020). "Co-immunoprecipitation in the renal cancer cell line CAKI which expresses wild type pVHL, showed that both endogenous USP9X and Smurf1 interact with pVHL (lane 2 versus lane 3 and 4)." (PMID 27517496, 2016).
autoimmune disease (3 papers, 2015 to 2020). A disorder resulting from loss of function or tissue destruction of an organ or multiple organs, arising from humoral or cellular immune responses of the individual to their own tissue constituents. "Interestingly, despite the positive role of USP9X in regulating TCR signaling, mice carrying T cell-specific deletion of USP9X display spontaneous T cell activation and develop a lupus-like autoimmune disease." (PMID 30054854, 2018).
colon adenocarcinoma (3 papers, 2012 to 2023). "The Mcl-1, Bcl-xL and USP9X expression patterns in human lung and colon adenocarcinomas were evaluated via immunohistochemistry." (PMID 23171055, 2012).
liver fibrosis (3 papers, 2023 to 2025). "Our data thus shed new lights into mechanisms underlying stellate cell activation and liver fibrosis and targeting USP9X/NRP1 might serve as potential target for liver fibrosis." (PMID 36653359, 2023). "Inactive USP9X ameliorated liver fibrosis in vivo via destabilizing NRP1." (PMID 36653359, 2023). "NRP1 deubiquitination mediated by USP9X enhances HSC activation, implying that targeting NRP1 or USP9X potentiates novel options in the treatment of liver fibrosis." (PMID 36653359, 2023). "Thus, targeting NRP1 or USP9X for treating liver fibrosis could bring up new therapeutic options." (PMID 36653359, 2023). "Moreover, USP9X expression inhibition attenuated HSC activation and liver fibrosis, accompanied by low NRP1 expression." (PMID 36653359, 2023). "Moreover, USP9X was found to be a critical deubiquitinating enzyme for the stability and high activity of NRP1 and NRP1 deubiquitination mediated by USP9X enhanced HSC activation and liver fibrosis." (PMID 36653359, 2023).
metastatic melanoma (3 papers, 2017 to 2024). A melanoma that has spread from its primary site to another anatomic site. "USP9X enhances the tumorigenic potential of metastatic melanoma by preventing proteasomal degradation of Ets‐1 through deubiquitination, a function reversible through USP9X knockdown or inhibition." (PMID 39678489, 2024). "Here we report that Ets-1 destruction is regulated by the deubiquitinating enzyme, Usp9x, and has major impact on the tumorigenic program of metastatic melanoma." (PMID 28198367, 2017). "Altogether, these results suggest that Usp9x overexpression is an early event in expansion of primary and metastatic melanoma, involving stabilization of Ets-1 to amplify NRAS expression." (PMID 28198367, 2017). "Together, these results suggest that Usp9x is overexpressed in metastatic melanoma and might contribute to stabilization of SOX2." (PMID 33613844, 2021). "Primary metastatic melanoma samples demonstrated moderately elevated Usp9x and SOX2 protein expression compared to tumors without metastatic potential." (PMID 33613844, 2021).
prostate tumor (3 papers, 2019 to 2024). "Compared to ERG-negative and benign tumor, USP9X expression is also increased in ERG-positive prostate tumor." (PMID 34112167, 2021). "WP1130, an inhibitor of USP9X, can prevents prostate tumor growth in vitro." (PMID 38531846, 2024). "Similar to our results, it could be demonstrated that depletion of USP9X increased ERG ubiquitination and subsequently suppressed prostate tumor growth." (PMID 30700749, 2019).
renal clear cell carcinoma (3 papers, 2016 to 2017). "In order to demonstrate USP9X negatively regulates pVHL in clear cell renal cell carcinoma (ccRCC) which is a VHL disease associated neoplasm, USP9X was knocked down in 786-0 cells stably expressing HA-tagged pVHL." (PMID 27517496, 2016). "Clinically, USP9x mRNA levels were reduced in several cancers with low USPx expression correlating with poor prognosis in renal clear cell carcinoma." (PMID 27462448, 2016). "Our data indicate that USP9x may be a useful biomarker for renal clear cell carcinoma." (PMID 27462448, 2016).
acute lymphoblastic leukemia (2 papers, 2016 to 2020). Leukemia with an acute onset, characterized by the presence of lymphoblasts in the bone marrow and the peripheral blood. "Although the underlying mechanisms were not shown, a recent study demonstrated that the USP9X inhibitor BRD0476 downregulated JAK2 signaling also in a subtype of acute lymphoblastic leukemia (ALL) that shows hyperactivation of JAK2 with or without the activating R683G mutation." (PMID 32050632, 2020).
acute pancreatitis (2 papers, 2023 to 2024). An acute inflammatory process that leads to necrosis of the pancreatic parenchyma. "In fact, we have previously found that the de-ubiquitinase probable ubiquitin carboxyl-terminal hydrolase FAF-X (USP9x) is an interactor of VMP1 in the context of the selective autophagy of zymogen granules during experimental acute pancreatitis." (PMID 37629161, 2023).
Angelman syndrome (2 papers, 2019). A neurogenetic disorder characterized by severe intellectual deficit and distinct facial dysmorphic features. "The Angelman syndrome disease gene ubiquitin-protein ligase E3A (UBE3A) and mental retardation disease gene ubiquitin specific peptidase, X-linked (USP9X) were also identified." (PMID 31703099, 2019). "Similarly, based on our results, we propose that attenuating the activity of USP9X may contribute to enhance the ubiquitination levels of UBE3A substrates that might be decreased in Angelman syndrome patients." (PMID 31130875, 2019). "Overall, our data shed light into the molecular mechanisms underlying Angelman syndrome, and reveal USP9X as a potential therapeutic target that may help restoring the non-pathological ubiquitination pattern on Angelman syndrome patients, and hence, ameliorate their symptoms." (PMID 31130875, 2019).
breast tumors (2 papers, 2017 to 2021). "Moreover, we demonstrated that overexpression of CEP131 in USP9X-deficient tumours could restore the growth of breast tumours." (PMID 28361952, 2017). "We also found that mutations in USP9X and USP7 have an ominous prognostic impact in luminal, HER2-enriched, and basal-like breast tumors." (PMID 33671201, 2021).
colitis (2 papers, 2018 to 2022). Inflammation of the colon. "In a colitis-associated intestinal cancer model, USP9X inactivation impairs intestinal regeneration." (PMID 35145062, 2022). "USP9X-deficient mice with DSS-induced colitis exhibit decreased body weight, indicating impaired gut regeneration." (PMID 35145062, 2022). "In addition, Usp9x inactivation impaired intestinal regeneration and increased tumor burden in colitis-associated intestinal cancer." (PMID 29346117, 2018). "The regulation of Fbw7 by Usp9x and increased proliferation of colonic crypts after acute colitis in Usp9xΔG mice prompted us to test the role of Usp9x in colitis-mediated CRC." (PMID 29346117, 2018). "Importantly, Usp9x mRNA levels were restored after recovery from colitis, and c-Myc and NICD1 returned to normal." (PMID 29346117, 2018). "Indeed, Usp9x was transcriptionally downregulated during the peak phase of colitis, and this resulted in a reduction in FBW7 protein levels with a concomitant increase in c-Myc and NICD1." (PMID 29346117, 2018). "Thus, negative regulation of c-Myc by Usp9x via direct stabilization of Fbw7 protects mice from colitis-mediated CRC." (PMID 29346117, 2018). "Notably, Usp9x and Fbw7 protein levels were dramatically reduced during the peak phase of colitis (day 7) and were restored to normal levels at later stages." (PMID 29346117, 2018). "Strikingly, Usp9x mRNA was reduced by around 50% during the disease peak, whereas Fbw7 mRNA was not significantly affected throughout the experiment, suggesting that decreased Fbw7 protein levels in response to colitis are the consequence of reduced Usp9x expression." (PMID 29346117, 2018). "In DSS-induced colitis, the USP9x and FBW7 protein levels are obviously decreased in the peak phase of colitis and return to normal levels during later phases." (PMID 35145062, 2022). "We first tested the protein and mRNA levels of Usp9x and Fbw7 in different disease phases of DSS-induced colitis." (PMID 29346117, 2018).
congenital heart disease (2 papers, 2023 to 2026). A heart disease that is present at birth. "Accumulating evidence has linked USP9X dysfunction to congenital heart disease (CHD), yet the specific genotype-phenotype correlations in this context remain poorly characterized." (PMID 41884638, 2026).
head and neck squamous cell carcinoma (2 papers, 2015 to 2021). A squamous cell carcinoma that arises from any of the following anatomic sites: lip and oral cavity, nasal cavity, paranasal sinuses, pharynx, larynx, and salivary glands. "USP9X mutations have been identified in several cancer types at significant levels in the TCGA studies: 11% of endometrial carcinoma, 9% of stomach adenocarcinoma and 9% of head and neck squamous cell carcinomas (cBioportal)." (PMID 26506417, 2015). "Following siRNA screening, we aimed to validate that depletion of USP9X caused a decrease in cell survival following high-LET radiation, but had no impact in response to low-LET protons, in both HeLa cells and also cells derived from head and neck squamous cell carcinoma." (PMID 34277417, 2021).
Hip dysplasia (2 papers, 2023 to 2025). The presence of developmental dysplasia of the hip. "USP9X was recently linked with syndromic cognitive impairment that includes hearing loss, dental defects, ventriculomegaly, Dandy–Walker malformation, skeletal anomalies (hip dysplasia), and other features showing a significant overlap with FOXC1-ARS." (PMID 37895297, 2023).
Lissencephaly (2 papers, 2013 to 2017). A spectrum of malformations of cortical development caused by insufficient neuronal migration that subsumes the terms agyria, pachygyria and subcortical band heterotopia. "A mutation in Dcx, which is unable to bind specifically to Usp9x, was detected in a patient with lissencephaly, suggesting this interaction is important in human cortical development." (PMID 23861879, 2013). "The interaction between Usp9x and DCX is clearly important for human CNS development as patients with point mutations in DCX that cannot bind Usp9x, develop lissencephaly." (PMID 23861879, 2013).
liver cancer (2 papers, 2024). An epithelial or non-epithelial malignant neoplasm that arises from the liver. "The deubiquitinase USP9x has been previously studied in several types of cancer including its involvement in the promotion of liver cancer through modulation of JAK2/STAT3 signaling." (PMID 39075050, 2024).
lung adenocarcinoma (2 papers, 2015 to 2024). A carcinoma that arises from the lung and is characterized by the presence of malignant glandular epithelial cells. "Based on this model system, Pemetrexed-mediated increase in Noxa resulted in suppression of Usp9X and subsequent depletion of Mcl-1 protein levels, rendering lung adenocarcinoma cells more sensitive to apoptotic stimuli." (PMID 26008975, 2015). "First, the gene expression data of lung adenocarcinoma (LUAD), the largest subgroup of NSCLC, patients from the TCGA uncovered that USP9x transcripts were significantly enriched in lung tumors (n = 535) compared to normal lung tissues (n = 59)." (PMID 39075050, 2024).
lymph node metastasis (2 papers, 2013 to 2023). "USP9X expression status was positively associated with both depth of invasion (p = 0.046) and lymph node metastasis (p = 0.032)." (PMID 24152793, 2013). "In this study, we observed that USP9X expression status was well-associated with depth of invasion (p = 0.046) and lymph node metastasis (p = 0.032)." (PMID 24152793, 2013). "Further, in a univariate Cox regression analysis in ESCC patients, the poor overall survival correlated with depth of invasion (HR 1.740, P = 0.033), regional lymph node metastasis (HR 1.910, P = 0.015), TNM stage (HR 1.842, P = 0.018) and USP9X expression (HR 2.192, P = 0.002)." (PMID 24152793, 2013).
non-small cell lung carcinoma (2 papers, 2023 to 2024). A group of at least three distinct histological types of lung cancer, including non-small cell squamous cell carcinoma, adenocarcinoma, and large cell carcinoma. "Here, we identify the deubiquitinase ubiquitin-specific peptidase 9 X-linked (USP9x) as a positive regulator of the proline biosynthesis pathway in non-small cell lung cancer (NSCLC)." (PMID 39075050, 2024).
oral cancer (2 papers, 2022 to 2026). "Ubiquitin-specific peptidase 9, X-linked (USP9X) deubiquitinates and stabilizes PD‐L1 in oral cancer cells." (PMID 41486149, 2026). "Moreover, pharmacological inhibition of USP9X potently induced cell death in oral cancer cells through rapid degradation of Mcl-1." (PMID 36045907, 2022). "Our recent studies have demonstrated the prognostic potential of USP9X in oral cancers." (PMID 36045907, 2022).
pancreatic adenocarcinoma (2 papers, 2016). "On the other hand, tumor suppressor functions have also been described in pancreatic adenocarcinoma and gingivo-buccal oral squamous cell carcinoma, highlighting the context-dependent role of USP9X in oncogenesis." (PMID 27602765, 2016).
Parkinson (2 papers, 2015 to 2025). "USP9X has been implicated in two neurodegenerative disorders: Parkinson (PD) and Diffuse Lewy Body Disease (DLBD)." (PMID 39974971, 2025).